C16orf46 (chromosome 16 open reading frame 46)
Synonyms: FLJ32702
Tractability: PROTAC: ubiquitination databases record sites on it.
Gene: Protein-coding gene on chromosome 16 (81,053,497 to 81,077,267, reverse strand). Ensembl gene ENSG00000166455.
Subcellular location (Human Protein Atlas): Nucleoplasm; Cytosol
Genetic constraint (gnomAD): Loss-of-function variants: 8 observed, 6.72 expected, observed/expected ratio (o/e) 1.19, 90% interval 0.69 to 1.85. That is too few expected variants to judge how well the gene tolerates losing a copy. Missense variants: 614 observed, 496.31 expected, observed/expected ratio (o/e) 1.24, 90% interval 1.16 to 1.32. Synonymous variants: 200 observed, 194.44 expected, observed/expected ratio (o/e) 1.03, 90% interval 0.92 to 1.16.
Homologues: Orthologues: chimpanzee C16H16orf46 (95% identical), macaque C20H16orf46 (88% identical), dog C16orf46 (70% identical), pig C16orf46 (66% identical), rabbit C16orf46 (62% identical), mouse 1700030J22Rik (55% identical), rat C19h16orf46 (53% identical).
Diseases named in the same sentence as C16orf46 in open-access papers:
C16orf46 is named in the same sentence as 2 diseases in open-access papers, as found by Europe PMC text mining. Sharing a sentence is not in itself a finding about the gene and the disease. The quoted sentences say what the papers report.
breast carcinoma (1 paper, 2013). "Other coding SNPs that could include causal variants producing synthetic associations (associations of rare with common SNPs of high penetrance) include SNPs in genes INS-IGF2, ZFYVE26, C16orf46, UNC13A, NRIP1 and CCDC91 for breast cancer and SNPs in SNED1 and PASK for prostate cancer." (PMID 23555315, 2013).
C16orf46 also shares sentences with these, for which no sentence is quoted: prostate carcinoma (1 paper).